STAT3 (signal transducer and activator of transcription 3)
Diseases named in the same sentence as STAT3 in open-access papers (continued):
Sharing a sentence is not in itself a finding about the gene and the disease.
cervical squamous cell carcinoma (9 papers, 2009 to 2024). A squamous cell carcinoma arising from the cervical epithelium. "For the JAK2/STAT3 pathways, many studies have documented the aberrant activation of STAT3 in HPV‐positive cervical squamous cell carcinoma (CSCC) cells and that this activation is strongly associated with poor prognosis." (PMID 32491253, 2020). "Since resveratrol can concurrently inactivates Wnt, Notch and STAT3 signaling in SiHa and HeLa cells, this multi-targeting compound would be of practical values in the prevention and treatment of cervical squamous cell carcinomas and adenocarcinomas." (PMID 25061499, 2014). "Our findings indicated that CD109 facilitates tumorigenicity and cancer aggressiveness, which might be mediated by EGFR/STAT3 signalling in cervical squamous cell carcinoma." (PMID 32507856, 2020). "In this study, we found that Stat3 was activated in 56.8% of cervical squamous-cell carcinomas in immunohistochemical analysis and the expression of activated Stat3 (p-Stat3) significantly correlated with a worse prognosis in patients with this disease by univariate analysis." (PMID 19638983, 2009). "Intriguingly, we found significant and positive correlations with expression levels of the OSM, OSMR, and STAT3 genes in cervical squamous cell carcinoma and endocervical adenocarcinoma (CESC) by analyzing the TCGA cohorts." (PMID 36551576, 2022). "Therefore, the aim of this study was to investigate whether the immunohistochemical expression of p-Stat3 can predict a poor prognosis in patients with cervical squamous-cell carcinoma." (PMID 19638983, 2009). "In cervical squamous cell carcinoma, CD109 expression enhanced EGFR-induced phosphorylation of STAT3, resulting in increased tumor aggressiveness and stemness activity." (PMID 33375719, 2020). "Moreover, CD109 is responsible for the induction of EGFR-mediated STAT3 regulation in cancer tumorigenicity and aggressiveness, which might reveal a potential molecular target for the development of an effective therapeutic strategy against cervical squamous cell carcinoma." (PMID 32507856, 2020).
endotoxemia (9 papers, 2010 to 2025). "It is well established that IL-6 plays a crucial role in mediating Stat3 activation, and age-related increases in plasma and cardiac IL-6 have been reported during endotoxemia." (PMID 40801652, 2025). "In this study, we have provided the evidence to demonstrate that HFD-induced endotoxemia promotes M1 macrophage infiltration in the ovaries, where they stimulate the overactivation of PFs by secreting cytokines and activating STAT3 signaling in the oocytes." (PMID 35563189, 2022). "Together with the data from the in vitro experiments, these results demonstrate that STAT3 inactivation and AMPK activation showed similar anti-inflammatory effect in mice with endotoxemia." (PMID 32210977, 2020).
hepatitis C (9 papers, 2014 to 2025). "When pooling all the patients from both cohorts together (n = 159), univariate analysis revealed that the hepatitis C virus (HCV) infection, tumor size, pathological satellite, lymph node metastasis, TNM stage and STAT3 levels were predictors of OS." (PMID 28032598, 2017).
Hyperinsulinemia (9 papers, 2016 to 2025). An increased concentration of insulin in the blood. "In contrast to the lack of correlation with serum leptin, TNF-α, IL-6, NF-κB and STAT3 activation, hyperinsulinemia in the foz/foz model remained a candidate enhancer of hepatocarcinogenesis." (PMID 30873458, 2016). "To simulate the effect of hyperinsulinemia we extended the previous network to add the regulation of IL-10 by insulin via the AKT pathway; and the STAT3-signaling cytokines: IL-10, IL-6, and IL-21 all use STAT3." (PMID 28651594, 2017).
metastasis (9 papers, 2009 to 2022). The spread or migration of cancer cells from one part of the body (where they first appeared) to another. "Positive p-Stat3 expression was observed in 71 of 125 (56.8%) cases and was significantly correlated with lymph node metastasis, lymph vascular space invasion, and large tumour diameter (>4 cm) by Fisher's exact test." (PMID 19638983, 2009). "Aberrant co-expressed of S1PR1 and p-STAT3 was not correlated with any clinicopathological factors, except for a positive correlation with metachronous liver metastasis (P = 0.022)." (PMID 31534132, 2019).
metastatic carcinoma (9 papers, 2011 to 2025). A carcinoma which has spread from the original site of growth to another anatomic site. "We conducted a phase I study of TTI-101, a first-in-class, selective small-molecule inhibitor of signal transducer and activator of transcription 3, in patients with advanced metastatic cancer." (PMID 39792482, 2025). "Meantime, MMP19 expression, or p-STAT3 and Ack-STAT3 of lung metastatic cancer tissues in the corresponding groups were also declined." (PMID 38560562, 2024). "STAT3 plays multiple functions and regulates many cellular processes, including the cell growth and apoptosis of metastatic cancer cells." (PMID 33466434, 2021). "The inhibitor of Rac/Cdc42 significantly decreased the activity of STAT3 in metastatic cancer." (PMID 37752569, 2023). "Interestingly, several well-known oncogenes linked to aggressive and metastatic cancer phenotype, including CXCL1, CXCL2, MYC, and BMP4, were included in this gene get, suggesting that BRD4 and STAT3 can coordinately regulate the oncogenic enhancer activity to promote tumor progression." (PMID 34290255, 2021). "Therefore, it is important to develop molecular drugs that can regulate both the JAK/STAT3 and TGF-β/SMAD signalling pathways to treat patients with metastatic cancer." (PMID 35655269, 2022).
NK cell leukemia (9 papers, 2016 to 2024). "A large subset (40%) of NK-cell large granular lymphocytic leukemia (LGL) harbors mutations of STAT3 gene, the same percentage of T-cell LGL (T-LGL) cases shows mutations of STAT3 and STAT5B genes." (PMID 38638855, 2024).
parasitemia (9 papers, 2012 to 2026). "Recently Chen's group found that the lethal strain of P. yoelli (XL) caused STAT3 activation which inhibited host protective immunity and resulted in high parasitemia and death." (PMID 22479586, 2012). "TLR7 promotes protective humoral immunity during non‐lethal P. yoelii infection by enhancing Tfh differentiation, survival, and B‐cell help via the STAT3/Ikzf2 pathway, whereas TLR7 deficiency impairs antibody responses and increases parasitemia." (PMID 41461395, 2026). "The most compelling result here is that skewing the hybrid-lineage cells toward a more committed Th1 phenotype in STAT3 TKO dramatically sped up clearance of parasitemia on reinfection." (PMID 32634740, 2020). "Both mice had reduced serum levels of Plasmodium-specific IgG2b, the Th1 isotype, suggesting that the strong positive effect on parasitemia in STAT3 TKO mice was due to improved Th1 memory." (PMID 32634740, 2020). "An independent role for IL-10 stimulating hepcidin secretion during patent parasitemia is supported by our experimental observations that IL-10 induces hepcidin in a dose-dependent manner through STAT3 phosphorylation." (PMID 24520384, 2014). "P. chabaudi-infected STAT3 TKO mice had consistently prolonged parasitemia and pathology." (PMID 32634740, 2020). "Still, therapeutic approaches that inhibit or promote STAT3 activation in NK cells could prove useful to improve host resistance when used appropriately in bacterial and parasitic infections." (PMID 31552035, 2019). "Chen's group reported that lethal Plasmodium yoelii (P.yoelii, XL) induced activation of STAT3 in the early phase of infection, the dominant pSTAT3 response may dampen the development of protective immunity which results in high parasitemia and death." (PMID 22479586, 2012). "To ensure parasite clearance after the first infection in both STAT3 TKO and WT, we treated with the anti-malarial drug chloroquine (CQ), which effectively eliminates low levels of P. chabaudi parasitemia." (PMID 32634740, 2020). "Our GO enrichment analysis shows that response to stimulus is the most significantly enriched biological process, which is highly consistent with host immune response mechanisms triggered by parasite infections, in which the core genes TNF, STAT3, STAT5A, PDGFB, ADRB2 and SMO were included." (PMID 41153368, 2025). "Strikingly, STAT3 TKO mice were 100% protected from reinfection, whereas T-bet-deficient mice had no Th1 memory cells and higher parasitemia." (PMID 32634740, 2020). "The mechanism of evolutionary pressure regulating this balance becomes clear in that the shift toward Th1 in STAT3 TKO animals, as well as the shift away from Th1 in the T-bet KO, as also shown for P. berghei ANKA, both prolong high parasitemia and pathology in the first infection." (PMID 32634740, 2020). "In the process of parasite infection, the JAK2/STAT3 signaling pathway also has a vital role." (PMID 31745105, 2019).
peritonitis (9 papers, 2012 to 2025). Inflammation of the peritoneum (tissue that lines the abdominal wall and covers most of the organs in the abdomen). "Similarly, in mice with Stat3 deficiency restricted to LysM+ neutrophils and macrophages susceptibility to peritonitis was increased in a cecal ligation and puncture (CLP) model." (PMID 31552035, 2019). "To understand how the effector properties of Th1 cells impact the contribution of STAT1 and STAT3 in acute resolving peritonitis, we have applied next-generation sequencing methods to examine the stromal response to inflammation." (PMID 37272871, 2023). "To understand the relationship between IL-6 and IFN-γ in these processes, we tracked the activity of STAT1 and STAT3 transcription factors in stromal tissue following peritonitis." (PMID 37272871, 2023). "This process requires IL-6R shedding from infiltrating neutrophils, which promotes IL-6 trans-signaling and STAT3-driven outcomes that instruct the tissue response to peritonitis." (PMID 37272871, 2023). "Using an alum-induced peritonitis model, the induction of the IL-10/STAT3 axis in response to type I IFN and LPS signaling was proposed as a predominant event to explain subsequent immunosuppression." (PMID 32104502, 2020). "T cell recruitment was impaired in IL-6−/− mice in a mouse model of peritonitis due to reduced chemokine expression which was mediated by STAT3 activation." (PMID 31694340, 2019). "Pre-conditioning of peritoneal leukocytes with SSC-DMSO for 3 h increased STAT-3 phosphorylation in the cellular extracts 2 h after the induction of Brewer thioglycollate (BTG) peritonitis in mice compared to SSC-DEVD." (PMID 22558449, 2012). "Here we found that peritonitis-induced the activation of Stat-3 and increased serum VEGF levels." (PMID 26498824, 2015). "This STAT-3 activation persisted and increased further after BTG-induced peritonitis in isolated peritoneal macrophages compared to both controls, indicating that MFG-E8 activated the STAT-3 pathway." (PMID 22558449, 2012). "In a murine model of acute peritonitis, resident macrophages, but not other cell types, were shown to play a regulatory role in inflammation through a STAT3 signaling pathway." (PMID 25371731, 2014).
pituitary tumor (9 papers, 2011 to 2023). A benign or malignant neoplasm affecting the pituitary gland. "In the current study, okadaic acid inhibited STAT3 serine dephosphorylation induced by pasireotide suggesting that this analog can act through phosphatase 2A in pituitary tumor cells carrying the FGFR4-R388 SNP." (PMID 27966451, 2017). "To examine the mechanisms underlying the differential effects of the somatostatin analogs on pituitary tumor cells, we investigated STAT3 serine phosphorylation." (PMID 27966451, 2017). "Moreover, the IL-6/JAK2/STAT3 pathway seems to be involved in the invasiveness of pituitary tumors by increasing the expression of MMP-9." (PMID 37958702, 2023). "It is equally plausible that inhibitors of STAT3 and those targeting oxidative phosphorylation may be of potential value in modulating pituitary tumors for therapeutic purposes." (PMID 22174695, 2011). "Finally, as somatostatin receptor genes (SSTR2, 3 and 5) are putative targets for miR-383, and STAT3 has been proposed as a promising target candidate for pituitary tumor immunotherapy, our results might also suggest that miR-383 could be a therapeutic target in corticotroph PitNETs." (PMID 32545591, 2020).
sarcopenia (9 papers, 2011 to 2025). Progressive decline in muscle mass due to aging which results in decreased functional capacity of muscles. "The involvement of IL-6 in STAT-3 signaling and its participation in sarcopenia development translates into increased weight loss." (PMID 33327591, 2020). "Both the proinflammatory pathways of NF‐κB and STAT3 are implicated in sarcopenia and cachexia." (PMID 39764565, 2025). "Meanwhile, DDIT4, FOXO1, and STAT3 exhibited significant differential expressions in the sarcopenia dataset GSE362." (PMID 41282482, 2025). "PE can also induce the expression of androgen receptor (AR), resulting in general anti-inflammatory effects through STAT3, counteracting STAT3-induced sarcopenia." (PMID 41011716, 2025). "STAT3 plays an essential role in sarcopenia driven by various factors, including aging, physical inactivity, poor nutrition, chronic diseases, hormonal changes, inflammation, oxidative stress, neurodegenerative processes, genetics, and medications." (PMID 39764565, 2025). "Indeed, IL-6 can promote muscle atrophy and fibrosis, contributing to sarcopenia, by increasing signal transducer and activator of transcription 3 (STAT3) signaling and protein catabolism." (PMID 35881303, 2022). "Correspondingly, the sarcopenia model showed marked differential expressions of BCL6, DDIT4, FLNA, FOXO1, NFKBIA, PGK1, and STAT3." (PMID 41282482, 2025).
serous ovarian cancer (9 papers, 2017 to 2026). "Seven studies assessed the association between STAT3/p-STAT3 expression and OS and PFS; 3 studies only included patients with serous ovarian cancer, one study only included patients with clear cell carcinoma." (PMID 34789292, 2021). "We further evaluated the linkage between p85α level and status of AKT and STAT3 activation in an independent set of in-house serous ovarian cancer samples (n = 43)." (PMID 30755611, 2019). "A microfluidic ChIP-based exosomes isolation method confirmed elevated pY-STAT3 levels in exosomes isolated from high-grade serous ovarian cancer cell lines and patients, implying that vesicles secreted from cancer patients have activated STAT3 signaling that could foster cancer metastasis." (PMID 31861720, 2019). "High-grade serous ovarian cancer tissue of chemo-naïve patients demonstrated strong expression of TNFR2 and STAT3 protein." (PMID 33809542, 2021).
uveal melanoma (9 papers, 2019 to 2024). A melanoma derived from melanocytes of the uveal tract. "According to our results, chelidonine increased the efficiency of constitutive serine phosphorylation, whereas it abrogated IL-6-induced tyrosine phosphorylation and nuclear translocation of STAT3 in the investigated human uveal melanoma cells." (PMID 34884773, 2021). "Interleukin-6, a major activator of STAT3, is present in elevated concentrations in uveal melanomas, suggesting contribution of dysregulated STAT3 activation to their pathogenesis." (PMID 34884773, 2021). "Taken together, we have shown that chelidonine affects STAT3 signaling in the uveal melanoma cells studied in our experiments." (PMID 34884773, 2021). "With the exception of constitutive tyrosine phosphorylation, which remained unaffected in the investigated uveal melanoma cells, chelidonine influenced both IL-6 induced activation and constitutive serine phosphorylation of STAT3 in a similar fashion." (PMID 34884773, 2021). "Here we show that chelidonine, the major alkaloid component of Chelidonium majus L., exerts opposing effects on IL-6-induced activation and constitutive serine phosphorylation of STAT3 in human uveal melanoma cells." (PMID 34884773, 2021). "Activation of DDR1/STAT3 signaling pathway by extracellular matrix remodeling promotes liver metastatic colonization (e.g., survival, outgrowth and stemness of cancer cells in the metastatic site) in uveal melanoma." (PMID 37709489, 2023). "Therefore, we studied the potential effects of this alkaloid on serine and IL-6-induced tyrosine phosphorylation of STAT3 in human uveal melanoma cells using flow cytometry and confocal microscopy." (PMID 34884773, 2021). "Here, we studied the impact of chelidonine on STAT3 signaling in human uveal melanoma cells." (PMID 34884773, 2021). "Here, we propose, for the first time, that retinal pericyte activation into CAFs is mediated by STAT3 phosphorylation and nuclear translocation following uveal melanoma interaction as indicated by the increased number of positive nuclei for phospho-STAT3 in HRPC cocultured with 92.1UM." (PMID 32756477, 2020). "Taken together, our results demonstrated the involvement of STAT3 signaling in the mechanism of action of chelidonine in human uveal melanoma cells, which raises the applicability of this alkaloid in the combinational or multimodal therapies of uveal melanomas and possibly other solid tumors." (PMID 34884773, 2021). "Furthermore, chelidonine predominantly induced apoptosis in OCM−1 cells, and exerted opposing effects on IL−6-induced activation and constitutive serine phosphorylation of STAT3 in OCM−1 and OCM−3 human primary uveal melanoma cells." (PMID 39598801, 2024).